CCK (cholecystokinin)
Diseases named in the same sentence as CCK in open-access papers (continued):
Sharing a sentence is not in itself a finding about the gene and the disease.
prostate carcinoma (6 papers, 2010 to 2023). A carcinoma that arises from epithelial cells of the prostate gland. "In the presence of adipocytes, prostate cancer cells actively secrete cholecystokinin (CCK), which stimulates the self-renewal of prostate CSCs and induces CTSB production in adipocytes." (PMID 37576397, 2023). "It is therefore surprising that CCK and its receptor were both found to be expressed by prostate cancer cells." (PMID 26700819, 2016). "The significant upregulation of CCK mRNA in prostate cancer cells upon co-cultured with adipocytes suggests that CCK is playing an important role in mediating the effect of adipocytes on CSC self-renewal." (PMID 26700819, 2016). "We found that co-culturing of prostate cancer cells with adipocytes resulted in CSC enrichment, which was associated with upregulation of cholecystokinin (CCK), a peptide hormone regulating fat digestion and satiety." (PMID 26700819, 2016). "In the presence of adipocytes, prostate cancer cells actively secrete the peptide hormone cholecystokinin (CCK), which not only stimulates prostate CSC self-renewal, but also induces cathepsin B (CTSB) production of the adipocytes." (PMID 26700819, 2016). "Considering that prostate cancer cells also express CCKBR and respond to CCK stimulation, the effects of high-fat diet on prostate tumor progression reported previously may well be a consequence of CCK elevation." (PMID 26700819, 2016).
asthma (5 papers, 2013 to 2025). "It is possible that the worsening of asthma symptoms associated with these clinical scenarios is related to elevated plasma CCK levels." (PMID 36599824, 2023). "The studies on the impact of CCK on asthma are, in turn, very limited." (PMID 38542187, 2024). "Despite these limitations, our study identifies seven core targets (HSP90AB1, CCNB1, CCK, CDK6, CASP9, NR3C1, and ERBB2) that offer promising avenues for developing novel asthma therapies." (PMID 41403444, 2025). "Similarly, conditions that lead to elevation of plasma CCK may trigger asthma symptoms." (PMID 36599824, 2023). "However, the potential in vivo function of CCK in AHR or asthma was not further explored, and it was not known which CCK receptor mediates the CCK action in the airway." (PMID 36599824, 2023).
gastroesophageal reflux (5 papers, 2018 to 2025). "High-fat foods release large amounts of cholecystokinin, which delays gastric emptying by stimulating vagal afferent fibers and predisposes to gastro-esophageal reflux." (PMID 38019753, 2023). "The presence of fatty foods in the duodenum can stimulate a release of cholecystokinin, which reduces the pressure of the lower esophageal sphincter, leading to gastroesophageal reflux." (PMID 31756947, 2019).
Hypertension (5 papers, 2019 to 2025). The presence of chronic increased pressure in the systemic arterial system. "Several genes (CCK, SLCO1A2, UGGT2) were identified as targets of drugs (diazoxide, nadolol, hydrochlorothiazide) used to treat hypertension, suggesting opportunities for drug repositioning and risk factor prevention." (PMID 40034430, 2025). "Taken together, in the early and advanced stages of hypertension, SY and NA exhibited vasorelaxing and anti-hypertensive effects via the NO and CCK systems, respectively." (PMID 31685714, 2019). "In SHR with advanced hypertension, NA exhibited potent vasorelaxation activity in a CCK-dependent manner, suggesting that the CCK system is important for blood vessels in SHR after the development of hypertension." (PMID 31685714, 2019). "In contrast, in SHR with advanced hypertension, NA exhibited the most potent vasorelaxation activity, and orally administered NA had long-lasting hypotensive activity in a CCK-dependent manner." (PMID 31685714, 2019). "Changes in CCK during stress provide a new avenue for analyzing the pathogenesis of hypertension." (PMID 39234603, 2024). "Cholecystokinin (CCK) is considered one of the environmental factors regulating hypertension." (PMID 39234603, 2024).
hypertriglyceridemia (5 papers, 2014 to 2023). A laboratory test result indicating elevated triglyceride concentration in the blood. "Hypertriglyceridemia is identified as a cause for gall bladder (GB) hypomotility as it reduces the GB sensitivity to cholecystokinin, a paracrine hormone that regulates the GB contraction." (PMID 25135323, 2014). "There is evidence that impaired gallbladder motility in individuals with hypertriglyceridemia is due to reduced sensitivity to cholecystokinin, which is relevant for gallbladder motility." (PMID 34465364, 2021). "In addition, hypertriglyceridemia consequently reduces gallbladder motility with decreased sensitivity to cholecystokinin." (PMID 33097057, 2020). "In a study investigating the association between gallbladder dysmotility and hypertriglyceridemia, decreased sensitivity to CCK, rather than reduced CCK release, was revealed to be the cause of impaired gallbladder motility in patients with high triglyceride blood levels." (PMID 29088261, 2017).
Hypoglycemia (5 papers, 2014 to 2025). A decreased concentration of glucose in the blood. "The application of orexin, insulin, PACAP, CRF, leptin, CART, CCK, and hypoglycemia (2 mM glucose) to the brain resulted in sympathetic nerve excitation." (PMID 30832213, 2019). "Together, these data identify CCKLPBN neurons, and specifically CCK neuropeptide, as glucoregulatory and provide significant insight into the homeostatic mechanisms controlling CR-responses to hypoglycemia." (PMID 25470549, 2014).
irritable bowel syndrome (5 papers, 2007 to 2025). Irritable bowel syndrome (IBS) is a chronic functional condition of the lower gastrointestinal (GI) tract characterized by abdominal pain or discomfort and disordered bowel habit (diarrhea, constipation, or fluctuation between the two). "In functional gastrointestinal disorders such as indigestion and irritable bowel syndrome, CCK signaling regulates the movement and secretion of the gastrointestinal tract, and abnormal CCK signaling may contribute to the symptoms of these disorders." (PMID 39948335, 2025). "The secretion of substance P (SP) and vasoactive intestinal polypeptide (VIP) are decreased, motilin and cholecystokinin (CCK) are increased after treatment with electrical acupuncture (EA) in rats with irritable bowel syndrome (IBS)." (PMID 32631387, 2020).
mood disorder (5 papers, 2018 to 2024). A cognitive disorder a disturbance in which the person's mood is hypothesized to be the main underlying feature. "It has been proposed that malfunctioning of the highly modifiable CCK+ interneuron syncytium is likely to result in mood disorders, because these cells carries information from subcortical pathways about the emotional, motivational and general physiological state of the animal." (PMID 29973870, 2018). "Due to its functions, CCK was suggested to be a target in the treatment of SCZ, mood disorders and drug addiction." (PMID 34976023, 2021).
neuroendocrine tumors (5 papers, 2010 to 2025). "Over the last decades, CCK expression has also been encountered in tumors (neuroendocrine tumors, cerebral astrocytomas, gliomas, acoustic neuromas, and specific pediatric tumors)." (PMID 28450850, 2017). "Anti-cholecystokinin (CCK) antiserum immunized with Ascaris proteins as the carrier protein reveals cross-reactivity of the Ascaris proteins to smooth muscle, cartilage, and some epithelial cells in human tissues, as well as to neuroendocrine tumors." (PMID 34203756, 2021). "Cholecystokinin is expressed at highly variable amounts in different neuroendocrine tumors, especially corticotrophic pituitary tumors, medullary thyroid carcinomas, phaeochromocytomas, and pancreatic islet cell tumors of which some may cause a specific CCKoma syndrome." (PMID 28450850, 2017).
Parkinson disease (5 papers, 2017 to 2025). A progressive degenerative disorder of the central nervous system characterized by loss of dopamine producing neurons in the substantia nigra and the presence of Lewy bodies in the substantia nigra and locus coeruleus. "CCK and GLP1 are implicated in neuroprotection and neurite outgrowth within the central nervous system (CNS), with GLP1R agonists offering therapeutic avenues for Alzheimer's and Parkinson's disease." (PMID 38013211, 2024). "Next, CCK/GLP-1 dual-agonist can be designed to treat Parkinson’s disease." (PMID 35368248, 2022).
alcohol dependence (4 papers, 2019 to 2024). Physical and psychological dependence on alcohol. "At last, we conducted logistic regression analysis and concluded that alcoholism, GAS, VIP, MTL, CCK, miR-155, and miR-21 were the risk factors of patients with AP." (PMID 34950438, 2021). "The gut microbiota dysbiosis may promote the development of alcohol dependence by regulating the endogenous cholecystokinin (CCK) and related receptors." (PMID 37962470, 2023). "Alcoholism, GAS, VIP, MTL, CCK, miR-155, and miR-21 were the risk factors of patients." (PMID 34950438, 2021). "The differential indicators in single factors (alcoholism, GAS, VIP, MTL, CCK, miR-155, and miR-21) were included and assigned." (PMID 34950438, 2021).
Alzheimer disease (4 papers, 2017 to 2026). A progressive, neurodegenerative disease characterized by loss of function and death of nerve cells in several areas of the brain leading to loss of cognitive function such as memory and language. "Moreover, a derivative of CCK was shown to regulate the mitochondrial function and improve the cognitive deficits in a mouse model of Alzheimer’s disease." (PMID 39334847, 2024). "Moreover, a CCK derivative regulated the mitochondrial function and improved the cognitive deficits in a mouse model of Alzheimer’s disease." (PMID 39334847, 2024).
anxiety disorder (4 papers, 2022 to 2025). A category of psychiatric disorders which are characterized by anxious feelings or fear often accompanied by physical symptoms associated with anxiety. "Cholecystokinin (CCK) is a gut–brain peptide that has been implicated in stress and anxiety disorders." (PMID 35056845, 2022). "Some researchers believe that both pain disorders and gastrointestinal disorders have been related to the brain chemical cholecystokinin (CCK) and may play a huge role in the development of GERD in patients with anxiety disorders." (PMID 36686114, 2022).
cardiac hypertrophy (4 papers, 2021 to 2022). "The development of myocardial hypertrophy can affect the cholecystokinin expression of myocardial tissues." (PMID 34497680, 2021). "The study is aimed at exploring the relationship between cholecystokinin expression and myocardial hypertrophy." (PMID 34497680, 2021). "However, it is unclear whether there is an increase in cholecystokinin expression in myocardial hypertrophy progression induced by abdominal aortic constriction." (PMID 34497680, 2021).
dyslipidemia (4 papers, 2020 to 2025). "However, CCK-8 levels were significantly higher in individuals with hyperlipidemia (p = 0.019), which could reflect alterations in appetite regulation and lipid metabolism associated with dyslipidemia." (PMID 40005054, 2025). "In recent years, there has been some research progress, such as studies on adiponectin, leptin, metabolic syndrome, cholecystokinin (CCK), and so on." (PMID 37893213, 2023).
Gallbladder dysfunction (4 papers, 2018 to 2025). "Rapid CCK infusion methods have been associated with falsely elevated or depressed ejection fractions, raising concerns about potential overdiagnosis or underdiagnosis of gallbladder dysfunction." (PMID 40525085, 2025).
memory impairment (4 papers, 2018 to 2025). "CCK has been associated with neuronal activation, as intraperitoneal treatment with CCK increases cFos expression in the locus coeruleus/subcoeruleus nucleus whereas CCK knockdown leads to memory impairment, assessed by the NORT49,50." (PMID 33208787, 2020). "Furthermore, CCK‐8 supplementation decreased escape latency and increased the number of platform crossings, indicating that CCK‐8 can alleviate spatial learning and memory impairment in aged dNCR model mice." (PMID 34402181, 2021). "Therefore, we conclude that the observed contextual episodic and spatial working memory impairments observed in SDV and CCK-SAP rats are unlikely to be secondary to surgical effects on body weight regulation." (PMID 29872139, 2018).
migraine (4 papers, 2018 to 2020). "In this study, we found that inhibition of GSK-3β (e.g., by AR-A014418) largely diminished SANP-induced expression and production of CGRP, as well as other known migraine-related factors (e.g., SP, CCK, PEG2) in cultured cells." (PMID 32276265, 2020). "The mechanism underlying this event involves GSK-3β activation in TGNs, likely in association with the inactivation of the PI3K/Akt pathway, while inhibition of GSK-3β effectively blocked SNAP-induced expression and production of CGRP and other migraine-related factors (e.g., SP, CCK, and PEG2)." (PMID 32276265, 2020). "Together, these results argue that activation of GSK-3β might functionally contribute to NO-induced expression and production of CGRP as well as other migraine-related factors (e.g., SP, CCK and PEG2) in TGNs." (PMID 32276265, 2020). "As for anti-migraine, HJZT can inhibits the expression of nociceptive transmission-associated neurotransmitters, including 5-HT, CGRP and CCK, which may be related to its upregulation of CB1R and downregulation of COX-2." (PMID 33014123, 2020). "Furthermore, GSK-3β inhibition resulted in a marked reduction in expression of CGRP as well as other migraine-related factors, including substance P, cholecystokinin, and prostaglandin E2." (PMID 32276265, 2020). "However, a dilating effect on arterial vessels after postprandial-increased CCK concentration was recognized and proposed as a possible pathogenesis for migraine attacks." (PMID 30469346, 2018). "Furthermore, CGRP can coexist with CCK in the trigeminal perivascular fibers to trigger migraine attacks by increasing cerebral blood flow." (PMID 30469346, 2018). "In the rat model of migraine, HJZT downregulated the expression of the CGRP and CCK mRNAs and upregulated 5-HT." (PMID 33014123, 2020). "Like CGRP, CCK is produced in the PAG and may be responsible for endogenous pain signaling system and its level increases in migraine." (PMID 32054443, 2020). "CGRP, as well as other neurotransmitters inflammatory factors such as SP, CCK, PGE2 released from TGNs and other type of cells (e.g., glial cells), leads to the central and peripheral sensitization, thereby triggering the onset of migraine." (PMID 32276265, 2020). "Furthermore, cholecystokinin (CCK) and calcitonin gene-related peptide (CGRP) may lead to the pathophysiological mechanisms shared by migraines and GSD." (PMID 30469346, 2018).
Nausea (4 papers, 2019 to 2023). A sensation of unease in the stomach together with an urge to vomit. "CCK was identified as the key regulator mediating nocebo nausea incidence, both peripherally and centrally." (PMID 37545429, 2023). "Understanding the receptors involved in this nausea response would be valuable when engineering antiobesity compounds as multiple anorectic peptides induce nausea at higher doses, including CCK, PYY3-36, and GLP-1." (PMID 31074796, 2019). "Recent studies demonstrated that exogenous CCK at high dosages could directly trigger nausea in rodents, and the process might be mediated by NTS that received gastrointestinal vagal afferent inputs." (PMID 37545429, 2023). "Given the hyperactivity of CCK and the HPA axis in other nocebo symptoms (e.g., pain), we explored the roles of these substances in nocebo nausea." (PMID 37545429, 2023).
sarcopenia (4 papers, 2017 to 2025). Progressive decline in muscle mass due to aging which results in decreased functional capacity of muscles. "We concluded that the older people with sarcopenia had significantly higher plasma concentrations of CCK, GLP-1, and PYY." (PMID 35565864, 2022). "We conclude that the older people in the sarcopenia group had significantly higher plasma concentrations of CCK, GLP-1, and PYY." (PMID 35565864, 2022). "In addition, we found older people with sarcopenia had significantly higher plasma concentrations of anorexigenic gastrointestinal hormones, including CCK, GLP-1, and PYY." (PMID 35565864, 2022). "The sarcopenia group had significantly higher fasting plasma concentrations of CCK, GLP-1, and PYY." (PMID 35565864, 2022). "CCK, GLP-1, and PYY in our older people (mean age, 86.9 years) with sarcopenia had significantly higher serum levels in the three groups." (PMID 35565864, 2022). "The mean CCK concentrations were 725.2, 385.4, and 1543.6 (pg/mL) in the non-sarcopenia, pre-sarcopenia, and sarcopenia group, respectively." (PMID 35565864, 2022). "We propose that anorexigenic gastrointestinal hormones, such as CCK, GLP-1, and PYY, might have important relationships with sarcopenia in the older people." (PMID 35565864, 2022). "The sarcopenia group had significantly higher fasting plasma CCK concentrations than both the non-sarcopenia and pre-sarcopenia groups." (PMID 35565864, 2022).
autism (3 papers, 2019 to 2021). Persistent deficits in social interaction and communication and interaction as well as a markedly restricted repertoire of activity and interest as well as repetitive patterns of behavior. "Intriguingly, we also found in our in silico transcriptomic analysis of CB1/CCK-positive interneurons that Necabs expression levels show strong positive correlations with other autism-associated genes." (PMID 33230531, 2021).
bulimia nervosa (3 papers, 2019 to 2025). A disorder characterized by recurrent episodes of binge-eating over which the individual feels a lack of control; these episodes of binge-eating are followed by recurrent compensatory behavior to prevent weight gain, usually self-induced vomiting. "By contrast, obese patients showed a delayed CCK “peak” and a similar abnormality may be found in non-uremic patients with bulimia nervosa, where the CCK “peak” is delayed and is 50% lower than those in control." (PMID 31191339, 2019).
cognitive decline (3 papers, 2021 to 2025). "Overall, these findings suggest that combining CCK administration with sound stimulation holds promise as a potential therapeutic approach for mitigating cognitive decline associated with auditory thalamocortical connectivity impairments or deficits in thalamocortical plasticity." (PMID 41264484, 2025).
COVID-19 (3 papers, 2020 to 2022). A disease caused by infection with severe acute respiratory syndrome coronavirus 2. "We suggest that the physiological role of these neuropeptides in neurotransmission, pain and vasodilation for cholecystokinin and substance P could be altered by binding to N. We speculate that N may link between viral replication and multiple pathways leading to long COVID-19 symptoms." (PMID 36432196, 2022).
eating disorder (3 papers, 2013 to 2025). A broad group of psychological disorders with abnormal eating behaviors leading to physiological effects from overeating or insufficient food intake. "Nevertheless, the role of CCK in the pathogenesis of eating disorders is still far from being known." (PMID 23349895, 2013). "In the past decades, CCK had been a “hot topic” in the field of eating disorder research since it had been shown that CCK induces satiety and limits meal size in rats and monkeys and it became evident that CCK is relevant for satiation in human subjects as well." (PMID 23349895, 2013). "Moreover, the malfunction of signaling molecules in the CCK/SRC/PI3K cascade reaction with leptin/JAK2/PI3K/STAT3 signaling pathway may lead to eating disorders." (PMID 36359184, 2022).